KBTBD13 (kelch repeat and BTB domain containing 13)
Description:
Substrate-specific adapter of a BCR (BTB-CUL3-RBX1) E3 ubiquitin ligase complex.
Synonyms: hCG_1645727; NEM6; HCG1645727
Tractability: PROTAC: UniProt records ubiquitination sites on it.
Gene: Protein-coding gene on chromosome 15 (65,076,746 to 65,079,948, forward strand). Ensembl gene ENSG00000234438.
Subcellular location: Cytoplasm
Pathways (Reactome):
Immune System: Antigen processing: Ubiquitination & Proteasome degradation
Metabolism of proteins: Neddylation
Gene Ontology:
Molecular function: protein binding; actin filament binding
Biological process: regulation of the force of skeletal muscle contraction; relaxation of skeletal muscle; proteasome-mediated ubiquitin-dependent protein catabolic process; protein ubiquitination
Cellular component: Cul3-RING ubiquitin ligase complex; cytosol; cytoplasm
Genetic constraint (gnomAD): Loss-of-function variants: 30 observed, 17.26 expected, observed/expected ratio (o/e) 1.74, 90% interval 1.26 to 1.96. The synonymous counts are far from expectation, so gnomAD's model fits this gene poorly and the ratio says little. Missense variants: 721 observed, 465.66 expected, observed/expected ratio (o/e) 1.55, 90% interval 1.46 to 1.65. Synonymous variants: 350 observed, 222.12 expected, observed/expected ratio (o/e) 1.58, 90% interval 1.44 to 1.72.
Gene-disease validity (ClinGen):
ClinGen rates the evidence that KBTBD13 causes each of these diseases.
nemaline myopathy 6 (autosomal dominant): Definitive.
Homologues: Orthologues: chimpanzee KBTBD13 (99% identical), macaque KBTBD13 (95% identical), dog KBTBD13 (94% identical), pig KBTBD13 (88% identical), mouse Kbtbd13 (86% identical), rabbit KBTBD13 (78% identical), tropical clawed frog kbtbd13 (52% identical), zebrafish kbtbd13a (51% identical). Paralogues in human: KLHL35 (25% identical), KLHL21 (25% identical), KLHL32 (25% identical), KLHL9 (25% identical), KLHL36 (24% identical), KLHL34 (24% identical), KLHL13 (24% identical), KLHL20 (24% identical), KLHL5 (24% identical), KLHL17 (23% identical), KLHL14 (23% identical), KLHL22 (23% identical), and 42 more.
Diseases named in the same sentence as KBTBD13 in open-access papers:
KBTBD13 is named in the same sentence as 15 diseases in open-access papers, as found by Europe PMC text mining. Sharing a sentence is not in itself a finding about the gene and the disease. The quoted sentences say what the papers report.
nemaline myopathy (8 papers, 2014 to 2024). Nemaline myopathy (NM) encompasses a large spectrum of myopathies characterized by hypotonia, weakness and depressed or absent deep tendon reflexes, with pathologic evidence of nemaline bodies (rods) on muscle biopsy. "In 2 individuals myopathy was associated with variants in the RYR1 gene, whereas in one individual nemaline myopathy caused by the KBTBD13 gene was diagnosed." (PMID 38758368, 2024). "It is worth noting that nemaline myopathy cases with KBTBD13 gene mutations are rarely reported, while the muscle pathology shows characteristic rods and cores lesions." (PMID 33742414, 2022). "Mutations in KBTBD13 gene were found to cause dominantly inherited nemaline myopathy, which features onset of weakness in early childhood and the presence of both nemaline bodies and core-like formations in the muscle fibers." (PMID 33742414, 2022). "Mutations in Kbtbd13 are associated with the NEM6 form of nemaline myopathy, which is characterized by the appearance of core-rods in electron microscopic images." (PMID 33114658, 2020). "An amino acid alignment of only the Kelch repeat regions shows that proteins involved in similar disease processes are clustered together (for example, KLHL40, KLHL41, and KBTBD13, all of which cause nemaline myopathy)." (PMID 24959344, 2014). "KBTBD13 mutations result in an autosomal dominant form of nemaline myopathy associated with cores in affected patients." (PMID 24959344, 2014). "In nemaline myopathy, all pathogenic KBTBD13 mutations identified to date in human patients were found in the Kelch repeats." (PMID 24959344, 2014). "Diseases associated with KBTBD13 include Nemaline Myopathy 6 and Childhood-Onset Nemaline Myopathy." (PMID 34070492, 2021). "Taken together, these results show that muscles of CM patients (excluding KBTBD13-related nemaline myopathy patients) as well as foetal muscles exhibit increased levels of transcripts encoding DNMTs and/or mainly, Class II HDACs." (PMID 36196089, 2022). "KLHL9, KBTBD13, KLHL40, and KLHL41 have been implicated in distal and nemaline myopathy." (PMID 31985165, 2020). "In the present study, we investigated whether the expression of different groups of transcripts are similarly impacted in muscles from CM patients with AD and AR RYR1-related myopathies, SELENON-related MmD, KBTBD13-related nemaline myopathy and MTM1-related XL-MTM." (PMID 36196089, 2022). "Unlike KLHL9 and KBTBD13 mutations that cause a dominant form of the disease, mutations in KLHL41, like KLHL40, result in an autosomal recessive form of nemaline myopathy." (PMID 24959344, 2014). "Localization studies have shown that KBTBD13 does not co-localize with α-actin (thin filament protein) or α-actinin (a Z-line marker), suggesting a different localization and mechanism of action than previously known proteins in nemaline myopathy, which primarily localize to thin filaments." (PMID 24959344, 2014).
nemaline myopathy 6 (2 papers, 2021 to 2024). Any nemaline myopathy in which the cause of the disease is a mutation in the KBTBD13 gene. "Dominant point mutations in KBTBD13 cause nemaline myopathy 6 (NEM6), which is clinically characterized by weakness and slow muscle relaxation." (PMID 39501809, 2024). "Mutations in the gene KBTBD13 have been associated with nemaline myopathy 6, characterized by childhood onset of progressive proximal muscle weakness." (PMID 34070492, 2021).
KBTBD13 also shares sentences with these, for which no sentence is quoted: congenital myopathies (2 papers); Brody disease (1); cancer (1); centronuclear myopathy (1); congenital muscular dystrophy (1); congenital myasthenic syndrome (1); congenital nemaline myopathy (1); distal myopathy (1); McArdle disease (1); myofibrillar myopathy (1); myopathy (1); Myotonia (1); myotonic dystrophy type 2 (1).